ENSG00000248993 (novel  protein)
Gene: Protein-coding gene on chromosome 6 (32,937,364 to 32,953,122, reverse strand). Ensembl gene ENSG00000248993.
Genetic constraint (gnomAD): Loss-of-function variants: 16 observed, 19.22 expected, observed/expected ratio (o/e) 0.83, 90% interval 0.56 to 1.26. Missense variants: 166 observed, 207.76 expected, observed/expected ratio (o/e) 0.8, 90% interval 0.7 to 0.91. Synonymous variants: 92 observed, 86.33 expected, observed/expected ratio (o/e) 1.07, 90% interval 0.9 to 1.27.